MYHAS (myosin heavy chain gene cluster antisense RNA)
Synonyms: linc-MYH
Gene: Long non-coding RNA gene on chromosome 17 (10,291,816 to 10,684,235, forward strand). Ensembl gene ENSG00000272975.
Diseases named in the same sentence as MYHAS in open-access papers:
MYHAS is named in the same sentence as 1 disease in open-access papers, as found by Europe PMC text mining. Sharing a sentence is not in itself a finding about the gene and the disease. The quoted sentences say what the papers report.
laryngeal carcinoma (1 paper, 2019). Carcinoma that arises from the laryngeal epithelium. "The risk coefficients suggested that LINC02154 and MNX1-AS1 are risk factors for laryngeal cancer (coef > 0), whereas MYHAS and LINC01281 appeared to be protective factors (coef < 0)." (PMID 31416476, 2019). "The risk coefficients in the multivariate Cox analysis revealed that LINC02154 and MNX1-AS1 are risk factors for laryngeal cancer, whereas MYHAS and LINC01281 appear to be protective factors." (PMID 31416476, 2019). "MYHAS and LINC01281 were associated with a better prognosis among laryngeal cancer patients." (PMID 31416476, 2019).